SNORD58C (small nucleolar RNA, C/D box 58C)
Gene: Small nucleolar RNA gene on chromosome 18 (49,489,245 to 49,489,308, reverse strand). Ensembl gene ENSG00000202093.
Gene Ontology:
Biological process: RNA processing
Cellular component: nucleolus
Homologues: Orthologues: macaque SNORD58 (100% identical), guinea pig SNORD58C (95% identical), pig SNORD58 (95% identical), rabbit SNORD58C (91% identical), tropical clawed frog SNORD58 (89% identical), zebrafish SNORD58 (75% identical). Paralogues in human: SNORD58A (80% identical), SNORD58B (75% identical), SNORD58 (72% identical).